MRPS31 (mitochondrial ribosomal protein S31)
Synonyms: MRP-S31; S31mt; IMOGN38; mS31
Tractability: Small molecule: a structure with a bound ligand is known. PROTAC: ubiquitination databases record sites on it; its protein half-life has been measured.
Gene: Protein-coding gene on chromosome 13 (40,729,128 to 40,771,351, reverse strand). Ensembl gene ENSG00000102738.
Subcellular location: Mitochondrion
Subcellular location (Human Protein Atlas): Mitochondria; Nucleoli
Pathways (Reactome):
Metabolism of proteins: Mitochondrial ribosome-associated quality control; Mitochondrial translation elongation; Mitochondrial translation initiation; Mitochondrial translation termination
Gene Ontology:
Molecular function: protein binding; protein domain specific binding; RNA binding; structural constituent of ribosome
Biological process: mitochondrial translation
Cellular component: mitochondrion; mitochondrial inner membrane; mitochondrial small ribosomal subunit
Genetic constraint (gnomAD): Loss-of-function variants: 27 observed, 36.22 expected, observed/expected ratio (o/e) 0.75, 90% interval 0.55 to 1.03. The upper end of that interval is the gene's LOEUF score, 1.03, which puts it in group 4 of 6, group 1 being the genes least tolerant of losing a copy. Missense variants: 386 observed, 412.44 expected, observed/expected ratio (o/e) 0.94, 90% interval 0.86 to 1.02. Synonymous variants: 151 observed, 150.02 expected, observed/expected ratio (o/e) 1.01, 90% interval 0.88 to 1.15.
Homologues: Orthologues: chimpanzee MRPS31 (99% identical), macaque MRPS31 (88% identical), dog MRPS31 (73% identical), pig MRPS31 (71% identical), guinea pig MRPS31 (68% identical), mouse Mrps31 (65% identical), rat Mrps31 (65% identical), tropical clawed frog mrps31 (44% identical), zebrafish mrps31 (40% identical), Drosophila melanogaster mRpS31 (28% identical), Caenorhabditis elegans mrps-31 (25% identical).
Diseases named in the same sentence as MRPS31 in open-access papers:
MRPS31 is named in the same sentence as 15 diseases in open-access papers, as found by Europe PMC text mining. Sharing a sentence is not in itself a finding about the gene and the disease. The quoted sentences say what the papers report.
hepatoma (5 papers, 2021 to 2025). "In an effort to elucidate how MRPS31 loss-mediated mitoribosomal defects modulate hepatoma cell activity, we identified COL1A1, a component of type I collagen, as a key downstream effector molecule." (PMID 34772924, 2021). "In this study, we demonstrated that COL1A1 is produced by hepatoma cells with MRPS31 loss, and COL1A1/DDR signaling could enhance cell invasiveness by activating the ZEB1-mediated EMT, thereby contributing to HCC aggressiveness." (PMID 34772924, 2021). "In hepatoma cell lines such as JHH5 and HepG2, MRPS31 suppression has been shown to enhance the invasiveness of hepatoma cells and disrupt the entire assembly of mitoribosomes." (PMID 38291374, 2024). "Together, our findings explain that MRPS31 loss is a key driver of mitochondrial dysfunction and HCC aggressiveness by modulating hepatoma cell invasiveness, suggesting MRPS31 loss as a novel prognostic marker of HCC malignancy." (PMID 34772924, 2021). "By employing hepatoma cell lines with SCNA-dependent MRPS31 expression (JHH5, HepG2, Hep3B, and SNU449), we demonstrated that MRPS31 deficiency is the key mechanism, disturbing the whole mitoribosome assembly." (PMID 34772924, 2021). "We proved that MRPS31 suppression is enough to induce mitoribosomal defects and subsequent mitochondrial dysfunction, eventually triggering hepatoma cell invasiveness." (PMID 34772924, 2021). "MRPS31 suppression enhanced hepatoma cell invasiveness by augmenting MMP7 and COL1A1 expression." (PMID 34772924, 2021). "However, inhibition of MRPS31 can lead to mitochondrial dysfunction, thereby enhancing the invasiveness of hepatocellular carcinoma cells.This suggests that MRPS31 may play a balancing role in maintaining mitochondrial function and cellular invasiveness in hepatocellular carcinoma cells." (PMID 40371222, 2025). "In these four hepatoma cell lines, DCN and mRNA expressions of RB1 exhibited a similar pattern as MRPS31, which was expected from the TCGA-LIHC analysis." (PMID 34772924, 2021). "Notably, the dependency of the clinical outcome on MRPS31 expression was a unique feature of HCC, implying a possible stronger dependence of hepatoma cell activities on mitochondrial dysfunction." (PMID 34772924, 2021).
ovarian carcinoma (3 papers, 2021 to 2025). A malignant neoplasm originating from the surface ovarian epithelium. "MRPL10, MRPL15, MRPL36, MRPL39, and MRPS16 were highly expressed in ovarian cancer, whereas MRPS31 showed the opposite tendency." (PMID 33934540, 2021). "Six MRPs (MRPL10, MRPL15, MRPL36, MRPL39, MRPS16, and MRPS31) related to HE4 in ovarian cancer were selected." (PMID 33934540, 2021). "Four studies suggested that the expression of MRPL15 was significantly increased in ovarian cancer, whereas one study concluded that the expression of MRPS31 was significantly decreased in ovarian cancer." (PMID 33934540, 2021). "Specifically, MRPS31 expression is associated with the established ovarian cancer biomarker, HE4 and increased expression is associated with poor survival and poor progression free survival in ovarian cancer." (PMID 39354291, 2024). "Hence, except for MRPS31 (whose amplification and deletion rates were 0.51% and 1.72%, respectively), amplification is the type of genetic variation with the highest incidence rate in these ovarian cancer‐related genes." (PMID 33934540, 2021). "Comparison of the relationship between these genes and the prognosis of ovarian cancer showed that overexpression of MRPL15, MRPL36, and MRPS31 may lead to poor OS and PFS in patients with ovarian cancer, among which MRPL36 showed the greatest prognostic significance." (PMID 33934540, 2021).
type 1 diabetes (3 papers, 2011 to 2022). "It was found that MRPS31 encodes ribosomal protein Imogen 38, which is a suggested target for autoimmune attack in type 1 diabetes." (PMID 36174000, 2022). "Lastly, MRPS31 encodes for a mitochondrial ribosomal protein that is involved in protein synthesis in mitochondria and is associated with type I diabetes." (PMID 21483694, 2011).
thyroid cancer (2 papers, 2014 to 2020). "The MRPS31 gene encodes for a mitochondrial ribosomal protein implicated in membrane protein synthesis essential for oxidative phosphorylation, and it has been associated with the progression of thyroid cancer." (PMID 32992457, 2020).
adenoma (1 paper, 2020). A neoplasm arising from the epithelium. "Of notice, the RT-PCR with junction specific primers of MRPS31 and SUGT1 genes was confirmed in both the adenomas and cancer tissues of three patients." (PMID 32992457, 2020).
breast carcinoma (1 paper, 2024). "In ovarian and breast cancer, MRPS31 is known to interact with metastasis-associated proteins." (PMID 39354291, 2024). "Additionally, there are multiple reports that MRPS31 is associated with a range of other pathways associated with breast cancer progression, including PIP3/AKT, hedgehog signalling, and wnt signalling." (PMID 39354291, 2024). "In breast cancer, MRPS31 is overexpressed in metastatic cell lines (MDA-MB231, MDA-MB468), and is known to interact with ACADSB [ACADSB is involved in fatty acid oxidation and has been associated with EMT and progression in a range of cancers, including breast cancer]." (PMID 39354291, 2024).
Infertility (1 paper, 2018). "The biological processes significantly represented among differentially expressed genes included mitochondrial function (Mrps31 and Trit1), cell senescence (Gpx6, Lamtor1 and Hist1h1e), cell growth (Hormad1 and Hormad2), infertility (Sycp3), and embryo development (Gli3)." (PMID 29851234, 2018).
squamous carcinoma (1 paper, 2023). "Other top genes include ODAD4, which is associated with ALL, LINC02568, which is linked to squamous carcinoma and MRPS31, which is a driver of carcinoma." (PMID 38023151, 2023).
cancer (5 papers, 2020 to 2024). A tumor composed of atypical neoplastic, often pleomorphic cells that invade other tissues. "This suggests that MRPS31 loss and the associated mitochondrial dysfunction may also occur in an early stage of cancer." (PMID 34772924, 2021). "In triple negative breast cancer, MRPS31 also interacts with CES1 and NPAS2, both of which are involved in pathways that have been implicated in the progression and metastasis of a variety of cancers." (PMID 39354291, 2024). "The role of RBPs in promoting cancer has been confirmed, and DROSHA, EXOSC8, HNRNPC, MRPS31, RPLP2, and SNRPB have also been reported to be related to the occurrence and development of a variety of tumors." (PMID 33981333, 2021). "Notably, Sanger sequencing and BLAST analyses among the amplicons produced from cDNA of polyps and carcinomas and MRPS31P5 showed higher sequence identity (100% similarity) than the fusion MRPS31-SUGT1 (90% similarity with exon 6 of MRPS31 and 98% similarity with exon 3 of SUGT1)." (PMID 32992457, 2020).
tumor (2 papers, 2021 to 2022). "Considering the key tumor-suppressive role of RB, the dependence of MRPS31 loss on RB1 deletion prompted us to ask whether MRPS31 loss is just an epiphenomenon during HCC development." (PMID 34772924, 2021). "Given the close association of MRPS31 with RB1, a core tumor suppressor, we questioned whether MRPS31 loss could substantially contribute to HCC development rather than be an epiphenomenon." (PMID 34772924, 2021). "Genes and proteins regulating the TCA cycle (PDHA1, SUCLG2, SUCLG1, and IDH2) as well as mitochondrial function (VDAC1, MRPS31, LARS2, OPA1, and MTIF2) showed higher transcripts and protein levels in Wnt‐high compared with Wnt‐low tumor entities." (PMID 35904277, 2022).
MRPS31 also shares sentences with these, for which no sentence is quoted: Insulin resistance (1 paper); liver cancer (1); Obesity (1); primary ciliary dyskinesia (1); type 2 diabetes (1).